GRK2 (G protein-coupled receptor kinase 2)
Diseases named in the same sentence as GRK2 in open-access papers (continued):
Sharing a sentence is not in itself a finding about the gene and the disease.
Insulin resistance (26 papers, 2009 to 2026). Increased resistance towards insulin, that is, diminished effectiveness of insulin in reducing blood glucose levels. "Elevated GRK2 contributes to the development of insulin resistance and associated vascular endothelial dysfunction in diabetic patients." (PMID 39438268, 2024). "GRK2 upregulation can cause alterations in the insulin signalling cascade, which can result in insulin resistance." (PMID 39438268, 2024). "For instance, chronic βAR stimulation causes the development of insulin resistance through an increase in GRK2 levels." (PMID 30538631, 2018). "Overstimulation of myocardial β2ARs and upregulation of GRK2 are associated with insulin resistance in the heart." (PMID 30538631, 2018). "The protection afforded by GRK2 downmodulation is apparent in the presence of concurrent relevant risk factors for insulin resistance and cardiovascular disease such as age and obesity after long-term HFD feeding." (PMID 27832814, 2016). "Furthermore, insulin resistance, glucose levels, and GRK2 expression emerge as strongly associated variables in a homeostasis model assessment of adipose-derived stem cells obtained from lean and obese human patients." (PMID 30837878, 2019). "If GRK2 upregulation causes insulin resistance, it is legitimate to speculate that its inhibition would have positive effects on cellular metabolism." (PMID 25147759, 2014). "Also, conditions associated to insulin resistance such as diabetes, hypertension or chronic activation of β adrenergic receptor, are characterized by elevated GRK2 levels." (PMID 25147759, 2014). "Thus, both local/circulating GPCR ligands associated with insulin resistance/hyperinsulinaemia, and insulin itself, contribute to the high GRK2 levels observed in insulin-resistant rodent/human tissues." (PMID 24265619, 2013). "Interestingly, GRK2+/− mice (expressing some 50% less protein than control littermates) show improved systemic insulin sensitivity in different insulin resistance models, and accordingly, inducible GRK2 downmodulation reverts key features associated to the diabetic phenotype in HFD-fed mice." (PMID 27832814, 2016). "Elevated GRK2 levels have been reported in vascular tissues under insulin resistance and hyperglycemia, where they impair eNOS activation and vascular relaxation." (PMID 41602450, 2026). "For example, inducible deletion of GRK2 in mice reverses diet-induced obesity and insulin resistance, mitigates hepatic steatosis, and improves insulin sensitivity." (PMID 41602450, 2026). "Excessive GRK2 activity is, therefore, considered a key contributor to endothelial dysfunction and insulin resistance, positioning GRK2 as a molecular bridge between metabolic dysregulation and vascular pathology." (PMID 41602450, 2026). "The inhibition of GRK2 fits well in this context, being able to both reduce insulin resistance and diabetes-dependent phenotypes." (PMID 33467677, 2021). "In this review, we will discuss the metabolic role of GRK2 in insulin resistance related conditions." (PMID 33467677, 2021). "G Protein Coupled Receptor Kinase type 2 (GRK2) has been identified as a mechanism of impaired glucose homeostasis in insulin resistance and its complications." (PMID 33467677, 2021). "The selective inhibition of the kinase potentiates insulin signaling both in vitro and in vivo suggesting that GRK2 mediates adrenergic insulin resistance while its inhibition increases insulin sensitivity." (PMID 33467677, 2021). "Particularly, GRK2 targeting is able to prevent and also to revert insulin resistance and excessive weight gain in different animal models of disease." (PMID 33020373, 2020). "Downregulation of GRK2 decreases steatosis and fibrosis in cardiac tissue and also prevents diet-induced hepatic insulin resistance and steatohepatitis." (PMID 33020373, 2020).
Insulin resistance (continued). "For example, in adipocytes GRK2-mediated endothelin-1-induced insulin resistance occurs by two mechanisms, one of which is a GRK2 kinase-independent inhibition of activation of Gαq/114." (PMID 31554835, 2019). "Overall, these results suggest that the increased levels of GRK2 that were detected during diet-induced obesity development in young male mice would favor insulin resistance and adiposity and promote a pro-inflammatory status in metabolically relevant tissues." (PMID 31752326, 2019). "GRK2 appears a promising target, given its established role in insulin resistance and in systolic heart failure." (PMID 30934608, 2019). "As this upregulation pattern of GRK2 with diet does not take place in young female animals, this vicious cycle linking GRK2 upregulation to increased insulin resistance and inflammation would be avoided." (PMID 31752326, 2019). "Previous studies showed that increased GRK2 levels were found in mononuclear cells in patients with metabolic syndrome while Tamoxifen triggered GRK2 deletion in mice leads to reversal of insulin resistance, improve fasting and impaired glucose tolerance." (PMID 34466413, 2018). "The GRK2 is also involved in inhibition of insulin signaling pathways, which results in insulin resistance." (PMID 34466413, 2018). "Further, GRK2 downregulation enhances basal cardiac insulin sensitivity and ameliorates insulin resistance in an animal model of high-fat diet-induced obesity." (PMID 30147654, 2018). "Impaired proteins ratio e.g. GGPPS, FAT, PTP-1B, GRK2, ATGL, FGF21 andPGC-1α presented in adipocytes and blood is responsible for causing insulin resistance and weight gain." (PMID 34466413, 2018). "In our study, we found that certain proteins levels were higher in the schizophrenic group than control group, which suggests their role in the pathogenesis of insulin resistance e.g. GRK2 protein level was found to be high in adipose tissue." (PMID 34466413, 2018). "In fact, GRK2, also known as βAR kinase 1 (βARK1), provides a link between altered vascular/tissue physiology in insulin resistance and impaired IRIS signaling." (PMID 24265619, 2013). "It has been reported that increased GRK2 levels mediate insulin resistance in myoblasts and adipocytes via a mechanism which involves sequestration of Gαq and IRIS." (PMID 24265619, 2013). "Of interest here is the finding that GRK2 mediates endothelin-1-induced insulin resistance via the inhibition of both Gαq/11 and insulin receptor substrate-1 pathways in 3T3-L1 adipocytes." (PMID 20204079, 2009). "It is GRK2 which mediates endothelin-1-induced insulin resistance via the inhibition of both Gαq/11 and insulin receptor substrate-1 pathways in these cells." (PMID 20204079, 2009). "In the current study, we have investigated the role of GRK2 in chronic ET-1-induced insulin resistance." (PMID 20204079, 2009). "Dysregulation of GRK2 expression or activity has been found to be involved in several pathological conditions, including cardiovascular disease, obesity, insulin resistance, and cancer where, GRK2 upregulation can affect β-adrenergic receptor function and exacerbate disease progression." (PMID 40076919, 2025). "Indeed, GRK2 expression is increased in key tissues in different experimental models of insulin resistance, and its downregulation ameliorates the alterations of glucose homeostasis and insulin signaling in response to different insults." (PMID 33467677, 2021). "Moreover, in a mouse model of obesity and insulin resistance, the inducible GRK2 ablation reverts the insulin-resistant and obese phenotype." (PMID 33467677, 2021). "Because GRK2 levels and activity have been reported to be enhanced in obesity and insulin resistance, in future studies it will be important to evaluate whether GRK inhibition enhances the effect of DPP-4." (PMID 34054727, 2021).
Insulin resistance (continued). "In this context, the inhibition of GRK2 could be a potential therapeutic strategy for those conditions correlated with insulin resistance due to the pleiotropic effects of the kinase." (PMID 33467677, 2021). "Moreover, inhibition of GRK2 activity leads to increased insulin sensitivity in in vitro and in vivo models of insulin resistance, demonstrating that GRK2 mediates insulin resistance through a kinase-dependent mechanism." (PMID 30934608, 2019). "However, with chronic stimulation,a vicious cycle begins, and increasingly high levels of Grk2 contribute to heartfailure progression.Furthermore, the Grk2 expression is related to insulin resistance and increasedmitochondrial stress." (PMID 31034522, 2019). "Our data suggest that GRK2 dosage might be involved in the sex and age-biased sensitivity to insulin resistance-related pathologies." (PMID 31752326, 2019). "Moreover, GRK2 KO mice displayed protection and enhanced insulin sensitivity in animal models of obesity and TNFα-induced insulin resistance." (PMID 30147654, 2018). "In addition, upregulation of β2AR enhances GRK2 expression that is related with βAR-induced insulin resistance in heart tissue and in animal models of insulin resistance." (PMID 30538631, 2018). "Moreover, upregulation of GRK2 impairs cardiac glucose uptake and promotes insulin resistance after MI." (PMID 30538631, 2018). "GRK2 is also involved in insulin signaling/IR dysfunction in other tissue as its levels are increased in muscle and adipose tissue in the animal models of insulin resistance as well as in lymphocytes from patients with metabolic syndrome." (PMID 30147654, 2018). "In addition, cardiac GRK2 levels increase, not only during HF, but also in insulin resistance status such as in ob/ob mice or animals fed with high fat diet." (PMID 30147654, 2018). "Thus, upon ET-1 activation, GRK2 associates with IRS-1 and promotes ET-1 mediated IRS-1 Ser612 phosphorylation and degradation which is associated with insulin resistance." (PMID 26474286, 2015). "GRK2 thus plays a role in chronic ET-1 induced insulin resistance by inhibiting IRS-1." (PMID 26474286, 2015). "On the other hand, inducible global GRK2 deletion models can help to determine whether systemic GRK2 downregulation can not only prevent but also revert certain diseases such as reported in the context of insulin resistance, overweight, and glucose." (PMID 30837878, 2019). "Moreover, GRK2 also plays an important role in the βAR-mediated cardiac insulin resistance." (PMID 30538631, 2018). "Our group has shown that GRK2 impairs cardiac glucose uptake and promotes insulin resistance after myocardial ischemia in an animal model, confirming that GRK2 could be an important hub in the regulation of cardiac function and metabolism during cardiac stress." (PMID 30147654, 2018). "However, it remains unknown whether altering glucose tolerance and insulin resistance regulates insulin-mediated Akt signaling-related GRK2 in T2DM models." (PMID 28814745, 2017). "Interestingly, insulin sensitivity in GRK2+/− mice is preserved after a HFD compared to WT littermates, indicating that a lower GRK2 dosage is able to protect animals against the development of diet-induced insulin resistance even in adult mice and after long-lasting HFD-induced obesity." (PMID 27832814, 2016). "Conversely, in middle-aged female mice, the GRK2 levels are increased by the HFD, as occurs in males, thus contributing to feeding-forward insulin resistance and inflammation-related pathological features." (PMID 31752326, 2019). "On the other hand, an insulin-resistance and obesity-related systemic metabolic milieu is known to enhance GRK2 upregulation, whereas a better-preserved metabolic homeostasis seems to attenuate such a HFD-mediated increase in GRK2 levels." (PMID 31752326, 2019).
Insulin resistance (continued). "Importantly, the GRK2 levels are elevated in adipose tissue, muscle, and liver in high-fat diet (HFD)-induced murine models of obesity and insulin resistance." (PMID 31752326, 2019). "Moreover, the deletion of GRK2 during a HFD restores a lean and insulin-sensitive phenotype, even after obesity and insulin resistance have been established." (PMID 31752326, 2019). "GRK2 has also been recently identified as a negative modulator of insulin signaling and systemic insulin resistance." (PMID 27832814, 2016).
cardiac hypertrophy (22 papers, 2009 to 2025). "The RGS domain of GRK2 is functional and inhibits Gq/11-mediated signaling, which is an established causative factor of myocardial hypertrophy." (PMID 30687708, 2018). "Both, human HF and animal models of cardiac stress such as myocardial infarction or genetic cardiomyopathies present upregulation of GRK2 protein expression associated with cardiac hypertrophy." (PMID 28759639, 2017). "The cardiac hypertrophy defect seen in Cul4a−/− mice can be partially rescued by deletion of one allele of Grk2." (PMID 27462452, 2016). "High levels of cardiac GRK2 are associated with the induction of cardiac hypertrophy and fibrosis." (PMID 38139099, 2023). "As GRK2 connects GPCRs to a multitude of downstream effectors, we hypothesized that GRK2 modulates signaling pathways linked to cardiac hypertrophy." (PMID 28759639, 2017). "GRK2 is up-regulated in experimental models of HF and is involved in the development of cardiac hypertrophy." (PMID 41155422, 2025). "This study investigated the cardioprotective effect of paroxetine in an animal model of cardiac hypertrophy (CH), focusing on its effect on GRK2-mediated NF-κB-regulated expression of prohypertrophic and profibrotic genes." (PMID 38139099, 2023). "In animal models of left ventricular hypertrophy, GRK2 inhibition attenuates cardiac hypertrophy by reducing NF-ĸB activity." (PMID 38139099, 2023). "Previous studies have reported that paroxetine has beneficial effects against pathological cardiac hypertrophy and fibrosis, compared to other existing SSRIs, because it acts as a GRK2 inhibitor." (PMID 38139099, 2023). "Three genes/proteins, in particular, CaMKIIδ, HDAC4, and GRK2 have been shown to act as central hubs or be directly involved in the induction of cardiac hypertrophy when misexpressed." (PMID 35890169, 2022). "Overall, these studies strongly suggest that the calpain-dependent modulation of the MDM2/GRK2 axis is a relevant event in cardiac hypertrophy downstream calpain overactivation." (PMID 35456920, 2022). "CaMKIIδ, HDAC4, and GRK2 have been shown to act as central hubs or be directly involved in the induction of cardiac hypertrophy when misexpressed." (PMID 35890169, 2022). "Remarkably, chronic administration of an oral calpain inhibitor prevented isoproterenol-dependent GRK2 upregulation, while hemizygous GRK2 mice showed attenuated myocardial hypertrophy." (PMID 35456920, 2022). "In this context, we designed a novel strategy of inhibition of GRK2 by mimicking the HJ loop of the kinase which was effective for the treatment of cardiac hypertrophy and of diabetes and its cardiovascular complications." (PMID 33256128, 2020). "GRK2 mediates Ang II–mediated cardiac contraction by interacting with Gαq, known as the final common trigger of maladaptive cardiac hypertrophy in situations of pressure overload." (PMID 32848782, 2020). "In line with this, Wortmannin treatment prevented GRK2 induced Akt and GSK3β phosphorylation, suggesting an essential role for GRK2-PI3Kγ interaction in GRK2 mediated cardiac hypertrophy." (PMID 28759639, 2017). "Our data show that enhanced GRK2 expression triggers cardiac hypertrophy by GRK2-PI3Kγ mediated Akt phosphorylation and subsequent inactivation of GSK3β, resulting in enhanced NFAT activity." (PMID 28759639, 2017). "The aim of the present study was to investigate the effects of GRK2 on cardiac hypertrophy and dissect potential molecular mechanisms." (PMID 28759639, 2017). "As PI3Kγ has been shown to be the crucial subunit in mediating cardiac hypertrophy, this indicates the GRK2/PI3Kγ complex as an essential link for GRK2 mediated cardiac hypertrophy." (PMID 28759639, 2017). "In order to further characterize GRK2 mediated effects on cardiac hypertrophy signaling, we exposed conditional GRK2KO mice to pressure overload." (PMID 28759639, 2017).
cardiac hypertrophy (continued). "We also detect a repression of PGC1α/β and of PPARα mRNA after HFD-driven cardiac hypertrophy in WT animals whereas this tendency is not only spared but, rather, inverted in GRK2+/− mice." (PMID 27832814, 2016). "This would indicate a possible amelioration of cardiac functionality upon GRK2 downregulation in this model, in line with previously reported results in other models of cardiac hypertrophy." (PMID 27832814, 2016). "Consistent with this notion, we report an increase in cardiac GRK2 levels in WT HFD-fed mice that correlates with enhanced cardiac hypertrophy and remodeling." (PMID 27832814, 2016). "GRK2 is up-regulated in cardiovascular diseases such as HF, cardiac hypertrophy, and hypertension." (PMID 41155422, 2025). "Transgenic mice with GRK2 cardiac-specific overexpression exhibited an increase in GRK2 synthesis and activity in the heart, which led to the impairment of β-AR signaling and eventually contributed to myocardial hypertrophy." (PMID 39451192, 2024). "It is well-established that paroxetine attenuates cardiac hypertrophy by inhibiting GRK2." (PMID 38139099, 2023). "Thus the downregulation of Pik3ca and subsequent inhibition in the binding of GRK2 to Pik3ca by wogonin has double significance to the therapy of myocardial hypertrophy." (PMID 30150938, 2018). "In this regard, GRK2 is a potential novel promising target for treatment of cardiac hypertrophy." (PMID 28759639, 2017). "Reduced adverse remodeling after reduction of GRK2 levels or activity could result from improved contractility or a critical role of this kinase in cardiac hypertrophy signaling pathways." (PMID 28759639, 2017). "In the present study we could demonstrate that enhanced GRK2 expression induced by GPCR stimulation mediates cardiac hypertrophy." (PMID 28759639, 2017). "We therefore propose a novel molecular role for GRK2 in the regulation of cardiac hypertrophy." (PMID 28759639, 2017). "For the first time we could demonstrate that GRK2 participates in cardiac hypertrophy by nuclear NFAT activation." (PMID 28759639, 2017). "Furthermore, recent data suggest that GRK2 kinase activity activates nuclear factor 'kappa-light-chain-enhancer' of activated B-cells (NF-κB), thus participating in cardiac hypertrophy." (PMID 28759639, 2017). "Using our established conditional GRK2 mouse line and in vitro studies on NRVMs we could demonstrate an essential role of GRK2 in cardiac hypertrophy." (PMID 28759639, 2017). "In the present study we investigated the role of GRK2 in the promotion of cardiac hypertrophy." (PMID 28759639, 2017). "Cardiac hypertrophy was blunted by conditional GRK2 knockout." (PMID 28759639, 2017). "Thus, GRK2 promotes cardiac hypertrophy in response to GPCR stimulation." (PMID 28759639, 2017). "As expected, cardiomyocyte-specific overexpression of GRK2 did not influence LV function and dimension as well as cardiac hypertrophy in sham mice compared to NLC sham animals." (PMID 33560342, 2022). "In contrast to Tg-RKIP mice, transgenic mice with myocardium-specific expression of the kinase-inactive GRK2-K220R mutant had a slightly improved cardiac function and showed no signs of cardiac hypertrophy." (PMID 30687708, 2018). "In contrast, the Gβγ inhibitor βARKct, which consists of the GRK2 c-terminal Gβγ binding domain, did not attenuate cardiac hypertrophy following TAC." (PMID 28759639, 2017). "However, we have evidence that GRK2 regulates NFAT and induction of cardiac hypertrophy via Akt and GSK3β." (PMID 28759639, 2017). "In addition, different groups provide evidence of non-canonical roles of the GRK2 isoform, including its ability to modulate cardiac hypertrophy." (PMID 35456920, 2022). "Nevertheless, as GRK2 interacts with a diversity of GPCR and non-GPCR targets, its pro hypertrophic effects are most likely not mediated via a single pathway but rather by modulation of signaling networks resulting in cardiac hypertrophy." (PMID 28759639, 2017).